ARG1 (arginase 1)
Diseases named in the same sentence as ARG1 in open-access papers (continued):
Sharing a sentence is not in itself a finding about the gene and the disease.
pancreatic adenocarcinoma (3 papers, 2012 to 2024). "Only one case of pancreatic adenocarcinoma out of 38 (2.6%) cases of MC and one of 12(8.3%) cases of CC showed positive immunoreactivity for arginase-1." (PMID 23111165, 2012). "The authors reported that it is not surprising to find a subset of the pancreatic adenocarcinomas included in their analysis demonstrated arginase-1 immunoreactivity." (PMID 23111165, 2012).
pneumonia (3 papers, 2017 to 2024). An acute, acute and chronic, or chronic inflammation focally or diffusely affecting the lung parenchyma, caused by an infection in one or both of the lungs (by bacteria, viruses, fungi, or mycoplasma.). "The percentage of MDSCs in PBMCs and the representative effectors, including Arg-1, S100A8/A9 and S100A12, were compared between the pneumonia group and the stable group." (PMID 35242775, 2022). "The frequency of MDSCs and effectors, including arginase-1, S100A8/A9, and S100A12, were significantly increased in the pneumonia group compared with the stable group." (PMID 35242775, 2022).
Spastic paraplegia (3 papers, 2019 to 2025). Complete loss of the ability to move the lower limbs accompanied by spasticity of the lower limbs. "Arginase 1 deficiency (ARG1‐D) is an ultrarare, metabolic disease which may cause spastic paraplegia, cognitive deficiency, seizures, and ultimately severe disability." (PMID 39512431, 2024).
squamous cell carcinoma (3 papers, 2021). A carcinoma arising from squamous epithelial cells. "Arginase-1 positivity is focal in squamous cell carcinomas and tightly linked to a distinct maturation stage of the epithelium which is comparable to the granular layer of the normal squamous epithelium." (PMID 34943588, 2021). "The pattern of arginase-1 immunostaining in squamous cell carcinomas closely resembled the findings in the normal keratinizing squamous epithelium." (PMID 34943588, 2021). "Furthermore, Arginase-1 positivity is also common in squamous cell carcinomas but limited to areas at the beginning of keratinization in these tumors." (PMID 34943588, 2021). "Studies have demonstrated arginase-1 expression in 0–7% of prostate cancer, 6% of adenocarcinomas of the ampulla Vateri, 84% of squamous cell carcinoma of the oral cavity and the larynx, and “high” expression in 47% of the 79 analyzed invasive breast carcinomas of no special type (NST)." (PMID 34943588, 2021). "As keratinization represents a feature of more mature squamous epithelium, it is not surprising that arginase-1 positivity was statistically linked to well-differentiated squamous cell carcinomas in this study." (PMID 34943588, 2021). "Arginase-1 positivity was only very rarely observed in non-hepatocellular, non-squamous cell carcinomas." (PMID 34943588, 2021).
acute lymphoblastic leukemia (2 papers, 2023 to 2024). Leukemia with an acute onset, characterized by the presence of lymphoblasts in the bone marrow and the peripheral blood. "We also found that ARG1 gene expression was restricted to the single erythroid cell cluster that we termed ARG1-positive Orthochromatic erythroblasts and that late Erythroid cells lose S100A9 and gain MZB1 gene expression in case of acute lymphoblastic leukemia." (PMID 39267736, 2024).
adenoma (2 papers, 2015 to 2020). A neoplasm arising from the epithelium. "Arginase 1 was highly expressed in tumor stroma, but undetectable in normal intestine adjacent to adenoma ApcMin/+ mice." (PMID 26378024, 2015). "We pooled CD11b+ cell infiltrates from adenomas from multiple Apc mice and probed the expression of UPR genes Il-23p19 and Arg1 relative to CD11b+ cells isolated from either the bone marrow or the spleen as controls." (PMID 32520957, 2020). "The EP4 antagonist decreased adenoma phosphorylation of both ERK and mTOR, inhibited expression of arginase 1 mRNA and protein." (PMID 26378024, 2015). "CD11b+ cells from APC adenomas had increased expression of UPR genes Il-23p19 and Arg1." (PMID 32520957, 2020).
amyotrophic lateral sclerosis (2 papers, 2017 to 2021). Amyotrophic lateral sclerosis (ALS) is a neurodegenerative disease characterized by progressive muscular paralysis reflecting degeneration of motor neurons in the primary motor cortex, corticospinal tracts, brainstem and spinal cord. "Arg1 and iNOS can be up-regulated during the progression of amyotrophic lateral sclerosis, and in motor neurons, Arg1 may confer protection from disease processes." (PMID 28285370, 2017).
anemia (2 papers, 2021 to 2025). A reduction in the number of red blood cells, the amount of hemoglobin, and/or the volume of packed red blood cells. "In humans with anemia, CECs expand and express ARG1 and ARG2 that suppress T-cells IFN-γ production." (PMID 34893694, 2021). "In line with our results, a recent study showed that anemia status influences the blood transcriptome with enrichment of erythrocyte differentiation genes as well as ARG1 in anemic children, but decreased signatures of CD4+ T cell activation and differentiation." (PMID 34893694, 2021).
aneurysm (2 papers, 2022 to 2023). Bulging or ballooning in an area of an artery secondary to arterial wall weakening. "Immunofluorescence staining examined the results observed in flow cytometry, showing that the Arg1+/IBA1+ macrophage (M2) count is higher than the iNOS+/IBA1+ macrophages (M1) in BBAs compared with that in the conventional saccular true aneurysms." (PMID 34970805, 2022). "In the in vivo study, we detected a gross lower expression level of CD68 and ARG1 (macrophage), Aggrecan (chondrocyte), OPN (osteoblast), ADIPQ (adipocytes), CD34 (mesenchymal cells), and LUM (fibroblasts) in the FAM3A-overexpressing aneurysm tissues compared with the matched Ad-sham tissues." (PMID 37660071, 2023).
asbestosis (2 papers, 2020 to 2025). A lung disorder caused by inhalation of asbestos fibers. "Lung macrophages isolated from humans with asbestosis showed a significant induction in TGFB1, IL10, ARG1, and MRC1 gene expression compared with healthy humans." (PMID 40208691, 2025).
brucellosis (2 papers, 2024 to 2025). Brucellosis is a bacterial infection that spreads from animals to people via unpasteurized dairy products or by exposure to contaminated animal products or infected animals. "The level of mRNA transcripts of Arginase-1 and iNOS were detected higher in vitro in MDSCs from brucellosis patients than that from healthy controls." (PMID 38352057, 2024).
cardiac hypertrophy (2 papers, 2013 to 2022). "Our data suggest that increased ARG1 mediates cardiac hypertrophy and perivascular fibrosis through increased synthesis of polyamines and proline." (PMID 23908657, 2013). "Our findings demonstrate that DOCA-salt induces cardiac hypertrophy and increases perivascular collagen deposition in WT mice, and that these effects are absent in ARG1+/− mice." (PMID 23908657, 2013).
cholestasis (2 papers, 2021 to 2024). Impairment of the bile flow caused by obstruction within the liver, or outside the liver in the bile duct system. "Tauro-β-muricholic acid (Tβ-MCA) and Glycocholic acid (GCA), the two most abundant cholestasis-associated primary BAs, remarkably promoted the expression of Arg1 and iNOS on neutrophils via p38 MAPK signaling pathway." (PMID 38951890, 2024). "Arginase 1 (Arg1) and nitric oxide synthase 2 (NOS2), which was contributed to neutrophils immunosuppressive by inhibiting T cells activation, were significantly upregulated in cholestasis liver metastasis." (PMID 38951890, 2024).
chronic asthma (2 papers, 2013 to 2025). An asthma that is characterized by the development of persistent airway inflammation and recurrent attacks of breathlessness and wheezing, which vary in severity and frequency. "In the first part of this study, we demonstrated that induction of an experimental acute exacerbation of chronic asthma is associated with striking upregulation of the expression by AM of arginase-1, FIZZ1, eotaxin-2/CCL24, and Ym1, all of which are markers characteristic of alternative activation." (PMID 23936781, 2013). "The target gene, ARG1, known for its role in NO production and its increased expression in chronic asthma, was subjected to RNA interference." (PMID 39896757, 2025). "Moving to in vivo studies in a murine model of chronic asthma, the PEI–isoprenaline complex exhibited remarkable efficiency in delivering ARG1 siRNA to ADRB2-expressing cells in BALF and lung tissues." (PMID 39896757, 2025). "Notably, the Arg1 siRNA/PEI–isoprenaline treatment outperformed all control groups, emphasizing the potential clinical relevance of this novel gene delivery system in the context of chronic asthma." (PMID 39896757, 2025).
Chronic colitis (2 papers, 2017 to 2021). A chronic inflammatory disease of the large intestine (colon, cecum and rectum). "The ratio of iNOS (M1-specific enzyme) to Arg-1 (M2-specific enzyme), indicative of arginine metabolism, was radically decreased in the MSC-Ex-treated colon of chronic colitis-induced mice." (PMID 28842625, 2017).
colorectal adenocarcinoma (2 papers, 2021 to 2024). The most common type of colorectal carcinoma. "The down-regulation of HAL and ARG1 by Wnt signaling is likely dependent on the type of tissue because the expression of HAL and ARG1 did not decrease in the Wnt-activated colorectal adenocarcinoma." (PMID 38684876, 2024).
demyelination (2 papers, 2019 to 2021). "The Arg1+Iba1+ cells were restricted to the demyelination lesion core and surrounded by other Iba1+ cells like CD86+Iba1+ cells at 10 dpi, consistent with the localization of CD206+Iba1+ and CD16/32+Iba1+ cells at 10 dpi." (PMID 31623610, 2019). "We showed that among HVCN1+ microglia/macrophages, the proportion of iNOS+ microglia/macrophages were about 80%, whereas the proportion Arg1+ microglia/macrophages were about 15%, indicating that within the focal demyelination lesion, the upregulated HVCN1 was mainly in iNOS+ microglia/macrophages." (PMID 34744634, 2021). "Considering the distinct M/M polarization patterns between LPC- and LPS-induced demyelination, correlations between OD ratio and M1 (CD16/32+Iba1+ or CD86+Iba1+) and M2 (CD206+Iba1+ or Arg1+Iba1+) proportions were calculated in LPC and LPS groups, respectively." (PMID 31623610, 2019).
diffuse large B-cell lymphoma (2 papers, 2020 to 2025). "In diffuse large B-cell lymphoma (DLBCL), the expression of TREM2 on M-MDSCs has been found to be associated with immunosuppressive functions, potentially by upregulating the expression of Arginase 1 (ARG1) to inhibit the proliferation of CD8+ T cells, thereby promoting tumor growth." (PMID 40242752, 2025). "On the other hand, the suppressive activity of M-MDSCs was shown to be independent of ARG1 and IDO in DLBCL (diffuse large B-cell lymphoma)." (PMID 33679700, 2020).
dry eye (2 papers, 2022 to 2025). "The dry eye condition significantly induced the M1-type macrophage marker, inducible nitric oxide synthase (iNOS/Nos2), rather than the M2-type macrophage marker, arginase 1 (Arg1)." (PMID 35681232, 2022).
E. coli infection (2 papers, 2022 to 2023). "We also examined the expression of iNOS and Arg1 protein using Western blot analysis and discovered that pretreatment with GYY4137 was able to effectively decrease the levels of iNOS protein whilst increasing Arg1 protein, thus partially reversing the changes caused by E. coli infection (P < 0.05)." (PMID 37644526, 2023). "Using intracellular flow cytometry, we then measured a subset of phenotypic markers (Arginase 1, iNOS, MHCII, and CD163), which classically represent pro- and antiinflammatory function following LOX-1 inhibition at 18–36 hours of E. coli infection." (PMID 36264633, 2022).
esophageal tumors (2 papers, 2020). "ARG1, as a regulator of T-cell fate is sixfold down-regulated in untreated primary esophageal tumors." (PMID 31960110, 2020). "ARG1, as a regulator of T-cell fate is sixfold downregulated in untreated primary esophageal tumors and fourfold downregulated in the NACT group in comparison to normal tissue." (PMID 31960110, 2020).
fibrosarcoma (2 papers, 2018 to 2020). A malignant mesenchymal fibroblastic neoplasm affecting the soft tissue and bone. "It has been reported that TAM isolated from the subcutaneous tumor established by C3 fibrosarcoma express higher level of ARG1 compared with normal splenic macrophages, and suppress T cell proliferation via ARG1-mediated mechanisms." (PMID 29670880, 2018).
gastric tumor (2 papers, 2015 to 2025). "Here we show elevated S100A8 and 9 as well as arginase-1, suggesting enhanced MDSC activity in stomach tumors deficient in IL-1RT1 signaling." (PMID 25528766, 2015). "For completeness, Arginase-1 staining was also negative in the remaining 2 intestinal lesions and the gastric tumor, confirming the absence of HCC metastasis in all tumors." (PMID 41159019, 2025).
Giardia infection (2 papers, 2019 to 2022). "Yet, in answer to Giardia infection, macrophages expressing arginase 1 and iNOS are recruited to the small intestine." (PMID 35482821, 2022). "We have previously demonstrated that Giardia infection leads to the accumulation of a population of CD11b+, F4/80+, ARG1+, and NOS2+ macrophages in the small intestinal lamina propria." (PMID 31455692, 2019). "We have previously reported an accumulation of ARG1- and NOS2-expressing macrophages in the small intestine during Giardia infection, and this expression was confirmed in the macrophages described in this study." (PMID 31455692, 2019). "We show that a population of F4/80+, CD11b+, CD11cint, CX3CR1+, MHCII+, Ly6C−, ARG1+, and NOS2+ macrophages accumulate in the mouse small intestine during Giardia infection." (PMID 31455692, 2019).
heart failure (2 papers, 2013 to 2025). Inability of the heart to pump blood at an adequate rate to meet tissue metabolic requirements. "Circulating arginase-1 level was found significantly higher in patients with heart failure, when compared to controls; and the level of circulating arginase-1 further increased with the severity of heart failure (significant increase between NYHA I/II and NYHA III/IV groups)." (PMID 24133491, 2013).
hepatic disease (2 papers, 2021 to 2024). "Patients with ARG1 deficiency develop symptoms in late infancy or pre-school age with progressive neurological manifestations and sometimes present with severe hepatic disease." (PMID 34646736, 2021). "Moreover, the mechanisms by which ARG1 deficiency results in either liver disorders or neurological disorders remain unknown." (PMID 34646736, 2021). "Moreover, some patients with ARG1 deficiency may present with severe hepatic diseases, such as neonatal cholestasis, acute liver failure, liver fibrosis, and/or hepatocellular carcinoma." (PMID 34646736, 2021).
HIV-1 infection (2 papers, 2021 to 2024). The type species of lentivirus and the etiologic agent of acquired immunodeficiency syndrome (AIDS). "In this study, we demonstrated that aging neutrophils accumulate in TN patients with HIV-1 infection and exhibit immunosuppression partially through PD-L1 and arginase-1." (PMID 34489929, 2021). "Previous findings have shown that elevated ARG1 or iNOS production may explain their suppressive mechanism during HIV-1 infection." (PMID 39742336, 2024). "In summary, we reveal that during HIV-1 infection, excessive aging of neutrophils induces immunosuppression of T cells, detected by increased PD-L1 and arginase-1 expression, and LPS may be an important inducer for the aging process." (PMID 34489929, 2021).
infarction (2 papers, 2020 to 2023). A localised pathological necrosis of tissue resulting from obstruction of the blood supply usually by a thrombus, an embolus, or vascular torsion. "Beyond the capacity as one of the key M2a macrophage biomarkers, Arg1 was found to play an important role in cardiovascular diseases, especially in healing of post-infarction hearts." (PMID 32203054, 2020). "Moreover, the expressions of IL-1β and Arg-1 decreased more obviously in cEVs-treated hearts than that receiving nEVs treatment, indicating that cEVs treatment showed better efficiency in modulating the cardiac inflammatory response post infarction." (PMID 37978390, 2023).
intrahepatic cholangiocarcinoma (2 papers, 2020 to 2021). A carcinoma that arises from the intrahepatic bile duct epithelium in any site of the intrahepatic biliary tree. "The aim of this study was to investigate the prognostic value of arginase-1 (Arg-1) and glypican-3 (GPC-3) in patients with intrahepatic cholangiocarcinoma (ICC)." (PMID 34715880, 2021).
iron deficiency (2 papers, 2018 to 2025). "Iron-enriched diet increased M2 marker Arg1 and Ym1 expression in liver and peritoneal macrophages, while iron deficiency decreased Arg1 expression." (PMID 29771935, 2018). "Indeed, the gene expression of Arg1, Ym1, IL-10 and Stat6, a series of genes expressed in M2 polarized macrophages, was increased after high iron diet condition, and, conversely, the expression of Arg1 and IL-10 was significantly decreased after dietary iron deficiency." (PMID 29771935, 2018).
kidney (2 papers, 2010 to 2024). "In the process of kidney injury, M1 macrophages promote inflammation and tubular cell apoptosis by secreting pathogenic factors such as IL-1β, TNF-α and IL-6; however, M2 macrophages reduce inflammation and promote renal recovery by secreting trophic factors such as IL-10, TGF-β and arginase-1." (PMID 38785317, 2024). "The implication of an androgen-regulated expression of ARG1 and ARG2 in prostate carcinogenesis requires further investigation." (PMID 20711410, 2010).
latent infection (2 papers, 2011 to 2025). "In summary, we identified that cryptococcal granulomas deriving from Δgcs1 latent infection are comprised by an inner myeloid core surrounded by ARG1+ type 2 responsive cells, an intermediate layer of stromal cells, and an outer cuff of T/B lymphocytes." (PMID 40568097, 2025). "Regardless, our data are consistent with a view that ROP16-mediated induction of arginase-1 functions to limit parasite replication, and that this is a strategy to facilitate host survival and establishment of latent infection to increase transmission potential." (PMID 21931552, 2011). "To determine whether ARG1 induction during Cryptococcus latent infection is due to cell-intrinsic STAT6 signaling, we generated mixed bone marrow chimeras whereby congenic markers can be utilized to recognize the genotype of cells competed in the same recipient." (PMID 40568097, 2025).
metastatic melanoma (2 papers, 2021). A melanoma that has spread from its primary site to another anatomic site. "Blocking CTLA-4 has been reported to dampen the accumulation of granulocytic MDSCs and reduce their arginase 1 (ARG1) production in the peripheral blood of patients with metastatic melanoma." (PMID 34620838, 2021).
myelofibrosis (2 papers, 2023). A partial or complete replacement of the bone marrow stroma by fibrous tissue. "Our previous studies have shown that among patients with MPN patients with myelofibrosis display a significantly reduced T-cell response to ARG1- and PD-L1-derived peptide epitopes as compared to patients with ET." (PMID 36911725, 2023). "In other words, the %Arg1 was reduced in MPN compared to controls and in those MPN diagnostic categories characterized by a BM fibrosis of grade ≥2 –that is overt PMF and post‐PV myelofibrosis‐ (p < 0.001)." (PMID 36524315, 2023).
myocardial inflammation (2 papers, 2017 to 2024). "In Coxsackie virus-induced myocarditis, the ~4-fold higher Arg1 expression in macrophages of female over male mice was attributed to skewing of the macrophage polarization towards an M2 phenotype in females, and towards an M1 phenotype in males." (PMID 29183288, 2017).